LINC00857 (long independently transcribed non-coding RNA 857)
Synonyms: HUMT
Gene: Long non-coding RNA gene on chromosome 10 (80,207,192 to 80,235,950, forward strand). Ensembl gene ENSG00000237523.
Diseases named in the same sentence as LINC00857 in open-access papers:
LINC00857 is named in the same sentence as 26 diseases in open-access papers, as found by Europe PMC text mining. Sharing a sentence is not in itself a finding about the gene and the disease. The quoted sentences say what the papers report.
pancreatic cancer (13 papers, 2016 to 2025). "Through a ceRNA-mediated mechanism, LINC00857 promotes the growth and invasion of pancreatic cancer cells." (PMID 36359832, 2022). "LINC00857 was reported to act as an oncogene in many cancers including hepatocellular carcinoma, lung cancer, pancreatic cancer and gastric cancer." (PMID 34346162, 2021). "We found that higher expression (FRKM log2 value > 0.5) of LINC00857 was presented in bladder, gastric, lung AD, cervix and pancreas cancers, and lower in prostate, thyroid, brain, blood and skin cancers (FRKM log2 value < 0.5)." (PMID 26862852, 2016). "Silencing LINC00857 inhibited the malignant behaviors of colorectal cancer and pancreatic cancer." (PMID 36060239, 2022). "LINC00857 expression is also mediated by m6A, and can promote the development of pancreatic cancer." (PMID 35692827, 2022). "m6A-mediated upregulation of LINC00857 promoted pancreatic cancer tumorigenesis." (PMID 34917609, 2021). "For example, overexpressed LINC00857 regulates the expression of E2F3 by binding to Mir-150-5p, ultimately promoting the tumogenesis and poor outcome of pancreatic cancer." (PMID 35676619, 2022). "Meanwhile, LINC00857 modulates E2F3 expression by binding to miR-150-5p, ultimately promoting tumorigenesis in pancreatic cancer." (PMID 35047414, 2021). "Furthermore, LINC00857 regulates the miR-130b/RHOA axis, which in turn enhances the malignant characteristics of pancreatic cancer." (PMID 36359832, 2022).
lung carcinoma (10 papers, 2016 to 2022). "It establishes the role of LINC00857 as potential driver of lung cancer pathogenesis and a diagnostic or prognostic biomarker of disease." (PMID 26862852, 2016). "In addition, LINC00857 was considered to be associated with low survival rate of patients and accelerates tumor progression in lung cancer." (PMID 32918541, 2020). "Furthermore, similarly to what we have found in bladder cancer, high LINC00857 expression was associated with shorter overall survival of patients with lung cancer suggesting its oncogenic role in cancer." (PMID 29856124, 2018). "Our data supports further examination of LINC00857's clinical utility in larger multi-institutional cohorts with outcome data to examine whether this gene has diagnostic and/or prognostic importance for lung cancer." (PMID 26862852, 2016). "Significantly, similarly to what we have discovered in PAAD, LINC00857 upregulation was connected with shorter survival time of patients with lung cancer, indicating its oncogenic role in cancer." (PMID 33661995, 2021). "For example, LINC00857 is upregulated in various cancer tissues, such as gastric cancer, ovarian cancer and lung cancer." (PMID 34753396, 2021). "We found p-AMPKa protein, not the total protein or mRNA, was significantly increased after LINC00857 knockdown with siRNA in lung cancer cells, and this increased expression occurred as early as 24 h." (PMID 33312753, 2020). "Su and colleagues demonstrated that LINC00857 silencing can decrease cell proliferation and induce apoptosis and autophagy in lung cancer cells." (PMID 33312753, 2020). "In this study, we found that LINC00857 silencing can impair cell proliferation in 14 different genomic alterations of lung cancer cell lines." (PMID 33312753, 2020). "In this study, we demonstrate that LINC00857 regulates cell proliferation in lung cancer cells with various genomic alterations and also found that LINC00857 can affect cell death signaling, including both cell apoptosis and autophagy." (PMID 33312753, 2020). "We have previously reported that LINC00857 was upregulated in lung cancer tissues, and its increased expression was correlated with poor survival in patients with lung cancer." (PMID 33312753, 2020). "Among these proteins, we found that the p-MET was the most significantly decreased protein after LINC00857 knockdown in PC-9 lung cancer cells." (PMID 33312753, 2020). "Towards this end, we generated a full length LINC00857 expression construct in a pcDNA-DEST53 vector and transfected the lung cancer cell line SK-LU-1, which possesses low endogenous levels of LINC00857 as compared to H1299 and H838." (PMID 26862852, 2016). "In order to confirm the FPKM value of LINC00857 detected by RNA-Seq and to select tumor cells for functional analyses, we measured LINC00857 expression in 33 lung cancer cell lines using qRT-PCR." (PMID 26862852, 2016). "The existing ENCODE data on DNA methylation and transcription factor binding/histone marks from Chip-Seq includes the lung cancer cell line A549 (which has high levels of LINC00857 expression)." (PMID 26862852, 2016). "Taken together, our study provides a comprehensive analysis of newly characterized LINC00857 in lung cancer." (PMID 26862852, 2016). "Silencing LINC00857 alleviated the proliferative capacity and facilitated the apoptosis, autophagy and radiotherapy sensitivity of lung cancer cells, suggesting that LINC00857 could act as a potential therapeutic target for LUAD." (PMID 36160408, 2022). "We conclude that p-AMPKa is required for LINC00857 to regulate autophagy in lung cancer cells." (PMID 33312753, 2020). "Our data reveal that LINC00857 plays a critical role in cell survival and death signaling and may provide a strategy for using LINC00857 as a potential biomarker and a therapeutic target for lung cancer." (PMID 33312753, 2020). "In this study, we uncovered new mechanisms of the LINC00857 role in lung cancer." (PMID 33312753, 2020).
lung carcinoma (continued). "LINC00857 was reported to play an oncogenic role in lung cancer." (PMID 31085800, 2019). "Recently, lncRNA LINC00857 is found to be overexpressed in hepatocellular carcinoma (HCC), and it promotes the progression of lung cancer." (PMID 34753396, 2021). "Thus LINC00857 may not only be a potential biomarker for diagnosis and prognosis of LUAD, but also play an important role in lung cancer progression." (PMID 26862852, 2016). "While, high LINC00857 expression was observed in 29 of the 33 cell lines tested, it was not expressed in 3 non-adherent lung cancer cell lines including 2 small cell lung cancers (H82 and H526) and one NSCLC derived from a metastatic lymph node (H1155) showed no expression." (PMID 26862852, 2016).
colorectal cancer (9 papers, 2021 to 2024). A primary or metastatic malignant neoplasm that affects the colon or rectum. "Loss-of-function experiment demonstrated that knockdown of LINC00857 restrained cell viability, proliferation and migration as well as epithelial mesenchymal transition and strengthened cell apoptosis in colorectal cancer." (PMID 37365581, 2023). "Next, we implemented WGCNA of the abundant RNA-seq data to determine molecules underlying the regulatory mechanism of LINC00857 in colorectal cancer." (PMID 36160408, 2022). "Notably, LINC00857 expression was negatively related to microsatellite instability and tumor mutation burden in colorectal cancer, implying poor reaction to immunotherapy when LINC00857 was highly expressed." (PMID 36160408, 2022). "These enriched pathways allowed us to better interpret the functions of LINC00857 in colorectal cancer." (PMID 36160408, 2022). "Unsurprisingly, our data verified that LINC00857 was essential for the proliferation of colorectal cancer cells." (PMID 36160408, 2022). "For more insight into the regulatory mechanisms of LINC00857 in colorectal cancer, we conducted a transcriptome sequencing analysis after LINC00857 knockdown with two independent siRNAs in HCT116 cells." (PMID 36160408, 2022). "Our study further elucidated the relevance of PIWIL4 expression with the immune features of colorectal cancer, which was in accordance with the roles of LINC00857." (PMID 36160408, 2022). "The FISH assays confirmed that LINC00857 expression was more widely expressed in colorectal cancer than in the normal tissues." (PMID 36160408, 2022). "To further investigate the functions of LINC00857 in colorectal cancer, we conducted RNA sequencing (RNA-seq) after LINC00857 knockdown in HCT116 cells." (PMID 36160408, 2022). "LINC00857 is upregulated and acts as an oncogene in colorectal cancer to promote colorectal cancer proliferation, migration and invasion by interacting with YTHDC1 and stabilizing SLC7A5." (PMID 35418193, 2022). "Based on the data in TCGA database, we firstly identified that LINC00857 was significantly upregulated in colorectal cancer patients." (PMID 34753396, 2021). "Targeting the HSF1/LINC00857/ANXA11 axis may provide a valuable therapeutic strategy against colorectal cancer." (PMID 36010849, 2022). "Our study found that LINC00857 accelerated the proliferation of colorectal cancer cells, which may offer a potential therapeutic target for colorectal cancer." (PMID 36160408, 2022). "Consequently, insights into the precise regulatory mechanisms of the HSF1/LINC00857/ANXA11 axis in colorectal cancer progression can further develop novel specific targeted drugs and diagnostic strategies for colorectal cancer." (PMID 36010849, 2022). "Interestingly, YTHDC1 ultimately combined with solute carrier family 7 member 5 (SLC7A5) and increased SLC7A5 mRNA stability to promote the proliferation and migration of colorectal cancer cells, implicating the critical role of LINC00857/YTHDC1/SLC7A5 axis in colorectal cancer progression." (PMID 37365581, 2023). "Targeting LINC00857 could dramatically impair the proliferative ability of colorectal cancer cells." (PMID 36160408, 2022). "Subsequently, we designed two specific siRNAs against LINC00857 and transfected them into HCT116 colorectal cancer cells." (PMID 36160408, 2022). "For example, LINC00857 contributes to diffuse large B-cell lymphoma proliferation and lymphomagenesis by sponging miR-370-3p, while lncRNA MIR17HG promotes colorectal cancer liver metastasis by sponging miR-138-5p." (PMID 35017465, 2022). "Thus, targeting LINC00857 may be feasible to impair the proliferation of colorectal cancer cells." (PMID 36160408, 2022). "These discoveries could likely help to illuminate the roles of LINC00857/PIWIL4 axis in colorectal tumorigenesis and development, provide a novel perspective for colorectal cancer immunotherapy, and make it possible to achieve more precise and efficient immunotherapy in the clinic." (PMID 36160408, 2022).
colorectal cancer (continued). "Considering that colorectal cancer patients with high-expression of LINC00857 may not be suitable for immune checkpoint inhibitors, targeting LINC00857 may be an ideal approach for these patients." (PMID 36160408, 2022).
gastric cancer (6 papers, 2021 to 2024). A primary or metastatic malignant neoplasm involving the stomach. "For example, LINC00857 was upregulated in gastric cancer tissue and had positive association with low survival rate and tumor size." (PMID 38721812, 2024). "Knockdown of LINC00857 can induce dysregulation of cell cycle and thus repress the proliferation of gastric cancer cells." (PMID 38721812, 2024).
lung adenocarcinoma (6 papers, 2019 to 2024). A carcinoma that arises from the lung and is characterized by the presence of malignant glandular epithelial cells. "In summary, we established and validated lncRNA prognostic models associated with angiogenesis in lung adenocarcinoma and determined the prognostic value of LINC00857, RBPMS-AS1, SYNPR-AS1 and LINC00460 in LUAD." (PMID 36999053, 2023). "LINC00857 is frequently dysregulated in varying cancers, which in turn exerts carcinogenic effects; however, its DNA methylation status in promoter region and molecular mechanisms underlying the progression of lung adenocarcinoma (LUAD) remain rarely understood." (PMID 38721812, 2024). "Accordingly, several researches have revealed that LINC00857 played an essential role in numerous tumors, such as lung adenocarcinoma, esophageal adenocarcinoma, and hepatocellular carcinoma." (PMID 33661995, 2021). "LINC00857 was reported to play oncologic roles in several cancers, for example, lung adenocarcinoma, bladder, gastric and liver cancer, and it has already been suggested that LINC00857 acts as a cell cycle regulator in lung adenocarcinoma by our previous work." (PMID 31085800, 2019). "For example, LINC00857 modulated lung adenocarcinoma progression by targeting miR-1179/SPAG5." (PMID 33661995, 2021). "LINC00857 via targeting the miR-1179/SPAG5 axis could regulate apoptosis in lung adenocarcinoma." (PMID 34367998, 2021). "It has been shown that LINC00857 enhances BIRC5-dependent radio-sensitivity of cancer cells, regulates apoptosis and glycolysis, and is identified as one of the prognostic markers for the early stage lung adenocarcinoma." (PMID 36105077, 2022).
ovarian carcinoma (6 papers, 2020 to 2025). A malignant neoplasm originating from the surface ovarian epithelium. "Mechanism experiments, including RNA immunoprecipitation, RNA pull‐down, and luciferase reporter experiments demonstrated that LINC00857 could regulate YAP1 (Yes1 associated transcriptional regulator) by competitively binding to miR‐486‐5p in ovarian cancer." (PMID 32918541, 2020). "According to the results, we discovered that LINC00857 was highly expressed in ovarian cancer cells, particularly in SKOV3 and A2780 cells." (PMID 32918541, 2020). "Meanwhile, the expression of LINC00857 in ovarian cancer cells (SKOV3, Caov3, and A2780) was also detected through qRT‐PCR analysis." (PMID 32918541, 2020). "Quantitative real‐time polymerase chain reaction assay was utilized to test the expression of LINC00857 in ovarian cancer tissues and cells." (PMID 32918541, 2020). "The upregulation of LINC00857 was further determined in 50 ovarian cancer tissues by comparing their corresponding non‐tumor tissues." (PMID 32918541, 2020). "In our study, bioinformatics prediction and mechanism investigation were implemented and we confirmed that miR‐486‐5p can bind with LINC00857 in ovarian cancer." (PMID 32918541, 2020). "In our research, we focused on the functions of LINC00857 in ovarian cancer and explore the regulatory mechanism between LINC00857 and Hippo pathway." (PMID 32918541, 2020). "In order to further investigate the regulatory mechanisms of LINC00857 in ovarian cancer, we first tested the distribution of LINC00857 in SKOV3 and A2780 cells through FISH and subcellular fractionation assays." (PMID 32918541, 2020). "Likewise, LINC00857 accelerated ovarian cancer progression and glycolysis by regulating the Hippo signaling pathway." (PMID 36160408, 2022). "In summary, LINC00857 accelerates ovarian cancer progression and glycolysis via regulating YAP1." (PMID 32918541, 2020). "In conclusion, LINC00857 regulates ovarian cancer progression and glycolysis via sponging miR‐486‐5p to upregulate YAP1 by modulating the Hippo signaling pathway, which may provide the new idea for curing ovarian cancer." (PMID 32918541, 2020). "Overall, LINC00857 accelerates cell growth, migration, and glycolysis in ovarian cancer." (PMID 32918541, 2020). "Overall, LINC00857 regulates YAP1 by competitively binding to miR‐486‐5p in ovarian cancer." (PMID 32918541, 2020). "Thus, we proved that LINC00857 inactivated the Hippo pathway in ovarian cancer." (PMID 32918541, 2020). "Nevertheless, the specific functions and mechanisms of LINC00857 in ovarian cancer remain unclear." (PMID 32918541, 2020). "Finally, we probed whether LINC00857 could aggravate ovarian cancer progression and glycolysis via targeting miR‐486‐5p/YAP1 axis through rescue assays." (PMID 32918541, 2020). "In a word, this study unveiled that LINC00857 regulates YAP1 by competitively binding to miR‐486‐5p and accelerates ovarian cancer progression." (PMID 32918541, 2020). "Taken together, LINC00857 inactivates the Hippo signaling pathway and YAP1 acts as the oncogene in ovarian cancer." (PMID 32918541, 2020). "LINC00857 (long intergenic nonprotein-coding RNA857) induces inactivation of the Hippo pathway by competitively binding to miR-486-5p in ovarian cancer and upregulating YAP1 expression, which in turn accelerates ovarian cancer progression and glycolysis." (PMID 36124026, 2022). "Accordingly, LINC00857 was discovered to take a larger proportion in the cytoplasm of SKOV3 and A2780 cells, which indicated the post‐transcriptional regulation of LINC00857 in ovarian cancer." (PMID 32918541, 2020).
esophageal adenocarcinoma (5 papers, 2019 to 2024). A malignant tumor with glandular differentiation arising predominantly from Barrett mucosa in the lower third of the esophagus. "For example, LINC00857 knockdown in esophageal adenocarcinoma reduced cell proliferative, invasive and migratory capabilities and induces apoptosis." (PMID 38721812, 2024). "Previous studies have indicated that the depletion of LINC00857 suppresses cell proliferation and induces cell apoptosis via decreasing some oncogenic proteins including c‐Myc in oesophageal adenocarcinoma." (PMID 34346162, 2021). "For example, LINC00857 exerts the oncogenic role in esophageal adenocarcinoma and knockdown of it represses the progression of esophageal adenocarcinoma." (PMID 32918541, 2020). "Furthermore, LINC00857 depletion blocked cell growth and promoted apoptosis in esophageal adenocarcinoma." (PMID 33661995, 2021).
hepatocellular carcinoma (4 papers, 2020 to 2024). A malignant tumor that arises from hepatocytes. "In hepatocellular carcinoma cells, LINC00857 knockdown stimulates apoptosis and constrains cell cycle progression in G1 phase." (PMID 38721812, 2024). "For example, LINC00857 was increased in hepatoma cell lines and depletion of LINC00857 inhibited the progression of hepatocellular carcinoma." (PMID 34346162, 2021). "LINC00857 silencing represses hepatocellular carcinoma (HCC) cell epithelial-mesenchymal transition (EMT) phenotype." (PMID 33312753, 2020).
lymph node metastasis (4 papers, 2020 to 2024). "Expression of LINC00857 was significantly associated with tumor diameter, pathological T, and lymph node metastasis." (PMID 35418193, 2022). "In addition, high expression of LINC00857 was also significantly associated with malignant features such as poor differentiation and lymph node metastasis." (PMID 34753396, 2021). "LINC00857 knockdown prominently reduced cell proliferation, impeded cell migration and invasion, and restrained lymph node metastasis, with enhancing radiosensitivity." (PMID 38721812, 2024).
bladder cancer (3 papers, 2018 to 2021). "Knockdown of LINC00857 significantly decreased cell viability of bladder cancer cell lines through the induction of apoptosis." (PMID 29856124, 2018). "Besides that, LINC00857 expression in the primary tumor was presented to predict muscle-invasive bladder cancer development and response to chemotherapy." (PMID 33661995, 2021). ",25, 26, 27, 28, 29 Knockdown of LINC00857 sensitizes bladder cancer cells to cisplatin." (PMID 33312753, 2020). "Furthermore, LINC00857 knockdown sensitized UM‐UC‐3 and T24 bladder cancer cells to cisplatin, via the negative regulation of the LMAN1 gene." (PMID 29856124, 2018).
triple-negative breast carcinoma (3 papers, 2020 to 2022). An invasive breast carcinoma which is negative for expression of estrogen receptor (ER), progesterone receptor (PR), and human epidermal growth factor receptor 2 (HER2). "In this study, we investigated the epigenetic alteration and biological effect of a novel triple-negative breast cancer lymph node-associated lncRNA HUMT (lncRNA highly upregulated in metastatic TNBC-lymph node, LINC00857), on cancer cell proliferation and metastasis." (PMID 32138762, 2020).